RTL4 (retrotransposon Gag like 4)
Description:
Involved in cognitive function in the brain, possibly via the noradrenergic system.
Synonyms: MART4; ZCCHC16; Mar4; FLJ46608; SIRH11; SIRH1
Tractability: Antibody: the Human Protein Atlas places it where antibodies can reach.
Gene: Protein-coding gene on chromosome X (112,082,965 to 112,458,566, forward strand). Ensembl gene ENSG00000187823.
Subcellular location (Human Protein Atlas): Nucleoplasm; Cytosol; Plasma membrane
Gene Ontology:
Molecular function: protein binding; nucleic acid binding; zinc ion binding
Homologues: Orthologues: chimpanzee RTL4 (98% identical), macaque RTL4 (93% identical), pig RTL4 (69% identical), dog RTL4 (68% identical), rabbit RTL4 (68% identical), mouse Rtl4 (58% identical), rat Rtl4 (57% identical). Paralogues in human: RTL1 (25% identical), RTL3 (20% identical), PEG10 (17% identical), RTL5 (14% identical), RTL10 (7% identical), RTL6 (5% identical), RTL8A (4% identical), RTL8B (4% identical), RTL8C (4% identical), LDOC1 (4% identical).
Diseases named in the same sentence as RTL4 in open-access papers:
RTL4 is named in the same sentence as 7 diseases in open-access papers, as found by Europe PMC text mining. Sharing a sentence is not in itself a finding about the gene and the disease. The quoted sentences say what the papers report.
autism spectrum disorder (4 papers, 2023 to 2024). A spectrum of developmental disorders that includes autism, and Asperger syndrome. "Retrotransposon Gag-like 4 (RTL4), a gene acquired from a retrovirus, is a causative gene in autism spectrum disorder." (PMID 39769499, 2024). "Among them, RTL4 (also known as SIRH11 or zinc finger CCHC domain-containing protein 16 (ZCCHC16)) has been implicated as a causative gene in autism spectrum disorder (ASD) through extensive screening of patients." (PMID 39769499, 2024). "RTL4/SIRH11 (aka Zinc Finger CCHC Domain-Containing Protein 16 (ZCCHC16) is a causative gene in autism spectrum disorders (ASD)." (PMID 37892118, 2023). "RTL4/SIRH11 (aka Zinc Finger CCHC Domain-Containint 16 (ZCCHC16) is implicated as a causative gene for autism spectrum disorders (ASD) and Sirh11/Zcchc16 KO mice exhibit increased impulsivity and diminished spatial memory, probably due to low levels of noradrenaline in the frontal cortex." (PMID 37842090, 2023).
Temple syndromes (1 paper, 2025). "In addition to RTL8A-C, RTL1 and RTL4 have been implicated in neurodevelopmental disorders, such as Kagami-ogata and Temple syndromes and ASD." (PMID 39875098, 2025).
neurodevelopmental disorder (2 papers, 2025). A behavioral and cognitive disorder with onset during the developmental period that involves impaired or aberrant development of intellectual, motor, or social functions. "Knockout mice lacking RTL4 show pronounced behavioral changes, such as increased impulsivity, impaired short-term memory, and poor adaptation to new environments, and it has been implicated as a causative gene in certain neurodevelopmental disorders in humans." (PMID 40362160, 2025).
RTL4 also shares sentences with these, for which no sentence is quoted: X-linked intellectual disability (2 papers); attention deficit-hyperactivity disorder (1); infection (1); mental disorder (1).